NCALD (neurocalcin delta)
Diseases named in the same sentence as NCALD in open-access papers:
NCALD is named in the same sentence as 36 diseases in open-access papers, as found by Europe PMC text mining. Sharing a sentence is not in itself a finding about the gene and the disease. The quoted sentences say what the papers report.
ovarian carcinoma (10 papers, 2014 to 2023). A malignant neoplasm originating from the surface ovarian epithelium. "Studies have found that NCALD was associated with the prognosis of several cancers, including non-small cell lung cancer, ovarian cancer, colorectal cancer, indicating its clinical potential as a prognostic biomarker." (PMID 37770991, 2023). "Previous study has reported that the TGF-β, NF-κB and ERK signaling pathways were associated with NCALD expression in epithelial ovarian cancer." (PMID 37770991, 2023). "The association between NCALD expression and prognosis in ovarian cancer patients was assessed using Kaplan-Meier plotter." (PMID 32228639, 2020). "The expression level of NCALD gene was associated with the prognosis of ovarian cancer and non-small cell lung cancer (NSCLC)." (PMID 31109331, 2019). "Low expression of NCALD in ovarian cancer is associated with poor OS and PFS." (PMID 32228639, 2020). "First, bioinformatics results showed that the genes expression related to ERK1/2 signal pathway was increased in the NCALD overexpression ovarian cancer patients." (PMID 32228639, 2020). "Our GSEA results showed that the genes expression related to ERK1/2 signal pathway, NF-kappaB signaling pathway and immune response pathway were increased in the NCALD overexpression ovarian cancer patients." (PMID 32228639, 2020). "We analyzed the relationship between NCALD expression and chemotherapy outcomes in ovarian cancer patients." (PMID 32228639, 2020). "The expression of NCALD in chemotherapy sensitive and chemotherapy resistant ovarian cancer patients was detected by TCGA data and clinical samples." (PMID 32228639, 2020). "Clinical samples were used to further verify the expression of NCALD in chemosensitive and chemoresistant ovarian cancer patients." (PMID 32228639, 2020). "Low expression of NCALD(neurocalcin delta) in peripheral blood of ovarian cancer patients predicts poor prognosis." (PMID 32228639, 2020). "As a new biomarker of chemotherapy sensitivity, NCALD was significantly down-regulated in chemotherapy resistance ovarian cancer patients." (PMID 32228639, 2020). "The key cellular processes and signal pathways of NCALD in ovarian cancer were identified by gene set enrichment analysis (GSEA)." (PMID 32228639, 2020). "NCALD expression is down-regulated in the poor prognosis group of advanced ovarian cancer which suggests that NCALD is a prognostic biomarker for these ovarian cancer patients." (PMID 31109331, 2019). "NCALD gene expression was significantly different in survival analysis, indicating that low expression of NCALD gene predicts poor prognosis in patients with ovarian cancer." (PMID 31109331, 2019). "It was determined that NCALD mRNA was down-regulated in the group with poor prognosis, having advanced stage and poorly differentiated tumors which implied NCALD a prognostic biomarker specific to these ovarian cancer patients." (PMID 27027352, 2016). "Epigenetic inactivation of NCALD may be one of the key factors leading to chemoresistance in ovarian cancer patients." (PMID 34289901, 2021). "The hypermethylation of NCALD and LAMA3 in promoters may be the cause of its downregulation in chemoresistance ovarian cancer patients." (PMID 34289901, 2021). "In ovarian cancer, Isaksson’s study showed that low expression of NCALD predicts poor prognosis." (PMID 32228639, 2020). "However, the molecular mechanism of NCALD in ovarian cancer and its relationship with chemotherapy outcomes is unclear." (PMID 32228639, 2020). "In summary, our study demonstrates that NCALD may activate the ERK1 / 2 signaling pathway in ovarian cancer." (PMID 32228639, 2020). "NCALD may activate the ERK1 / 2 signaling pathway in ovarian cancer." (PMID 32228639, 2020). "It has also been shown that LYAR, PDIA3, NOP14, NCALD, MTSS1 and CYP1B1 are correlated with the prognosis of ovarian cancer." (PMID 34696677, 2021).
ovarian carcinoma (continued). "Previous literature reported that NCALD might be related to ERK1/2 signaling pathway, NF-κB signaling pathway, TGF-β signaling pathway and immune response pathway in ovarian cancer." (PMID 37770991, 2023). "In addition, LYAR and five other genes (PDIA3, NOP14, NCALD, MTSS1, and CYP1B1) showed potential as prognostic biomarkers for radical ovarian cancer." (PMID 34696677, 2021). "This shows that NCALD, LAMA3 and ITGB6 may influence each other and participate in the chemotherapy resistance of ovarian cancer together." (PMID 34289901, 2021). "Important new findings include the identification of two new key genes, NCALD and LAMA3, which may drive the acquired resistance of ovarian cancer." (PMID 34289901, 2021). "A gene expression profile study with whole blood cell mRNA from ovarian cancer patients revealed LYAR and other five genes (PDIA3, NOP14, NCALD, MTSS1 and CYP1B1) as potential prognostic biomarkers for curative and postoperative supportive therapies for ovarian cancer." (PMID 26413750, 2015). "Although NCALD and LAMA3 are genes that show both methylation and expression changes, the methylation of the ITGB6 gene may also play a role in the chemoresistance of ovarian cancer." (PMID 34289901, 2021). "In addition, the molecular mechanism of NCALD in ovarian cancer and its relationship with chemotherapy sensitivity has not been reported." (PMID 32228639, 2020).
breast carcinoma (4 papers, 2017 to 2024). "Our above results revealed downregulated expression of NCALD in breast cancer tissues and breast cancer cells, indicating the tumor-suppressive role of NCALD in breast cancer." (PMID 37770991, 2023). "Significantly, NCALD expression was markedly downregulated in breast cancer tissues compared with normal tissues." (PMID 37770991, 2023). "Regarding the list for down regulated genes associated with breast cancer, 3 genes were also present in our list (HLA-DPA1, PCDH9 and NCALD)." (PMID 29108258, 2017). "Besides, the expression of lncRNA NCALD in serum of luminal breast cancer patients was also unclear and its implications for liquid biopsy applications should be explored in the following study." (PMID 38291441, 2024). "In this study, we found that NCALD was downregulated in breast cancer tissues." (PMID 37770991, 2023). "Moreover, immunohistochemistry (IHC) showed higher expression of NCALD in normal tissues than breast cancer tissues according to Human Protein Atlas database." (PMID 37770991, 2023). "Among these genes, we hypothesized that NCALD, the tumor suppressor gene, might be a potential target of MIDEAS-AS1 in breast cancer." (PMID 37770991, 2023). "In addition, the ChIP followed by qPCR assays was subsequently performed in Flag-MATR3 transfected breast cancer cells with or without MIDEAS-AS1 overexpression to determine the effect of MIDEAS-AS1 on MATR3 recruitment to the NCALD promoter." (PMID 37770991, 2023). "However, the function role and molecular mechanism of NCALD in breast cancer has not been reported." (PMID 37770991, 2023). "However, there is no report about the function of NCALD in breast cancer." (PMID 37770991, 2023).
schizophrenia (4 papers, 2012 to 2025). A major psychotic disorder characterized by abnormalities in the perception or expression of reality. "Of these genes, 9 genes had protein expression detected in the dorsal lateral prefrontal cortex (dlPFC) and 2 of those (PRKDC and NCALD) were significantly differentially regulated in schizophrenia." (PMID 40181191, 2025). "In genetic rat models of schizophrenia, NCALD expression was downregulated and in NCALD knockout mice, it was linked to adult hippocampal neurogenesis." (PMID 40253403, 2025). "We also observed significant regulation of NCALD protein expression in the dlPFC in schizophrenia." (PMID 40181191, 2025). "NCALD levels are downregulated in the brains of patients with Alzheimer’s disease and in a genetic mouse model of schizophrenia." (PMID 30853885, 2019).
bipolar disorder (3 papers, 2018 to 2025). A disorder of the brain that causes unusual shifts in mood, energy, activity levels and the ability to carry out day-to-day tasks. "Additionally, single nucleotide polymorphisms (SNPs) in NCALD have been associated with autism and bipolar disorder." (PMID 30853885, 2019). "Additionally, NCALD SNPs have been associated with bipolar disorder." (PMID 40253403, 2025). "The NCALD and ZNF536 genes have been shown to be linked with bipolar disorder." (PMID 30034349, 2018).
lung carcinoma (3 papers, 2016 to 2020). "NCALD expression is down-regulated in lung cancer tissues, while low NCALD expression levels are associated with poor prognosis in non-small cell lung cancer (NSCLC) patients." (PMID 31109331, 2019).
Obesity (3 papers, 2017 to 2023). Accumulation of substantial excess body fat. "Experiments have shown that NCALD is a potential hippocampal memory-related factor related to obesity." (PMID 35795788, 2022). "Our findings suggested that the memory-impairing effects of diet-induced obesity might potentially be mediated by down-regulated NCALD within the hippocampus." (PMID 29937895, 2017). "Furthermore, NCALD is proved to be a potential hippocampus-memory related factor related to obesity." (PMID 29937895, 2017).
spinal muscular atrophy (2 papers, 2019 to 2021). A motor neuron disease that affect the muscles, and characterized by muscle weakness and atrophy resulting from progressive degeneration and irreversible loss of the anterior horn cells in the spinal cord (i.e., lower motor neurons) and the brain stem nuclei. "The interaction with NCALD is also likely to mediate trafficking of S100B in response to calcium both in glia and neurons: NCALD is known to bind to cytoskeletal elements and clathrin and regulate endocytosis in spinal muscular atrophy." (PMID 33466232, 2021). "Recently, we have shown that reduced NCALD levels protect against spinal muscular atrophy (SMA) in individuals carrying homozygous deletion of SMN1 and only four SMN2 copies." (PMID 30853885, 2019). "Neurocalcin delta (NCALD) is a brain-enriched neuronal calcium sensor and its reduction acts protective against spinal muscular atrophy (SMA)." (PMID 30853885, 2019).
Atrophy (1 paper, 2023). Any weakening or degeneration, especially through lack of use. "For example, low NCALD expression protects against myeloid muscle atrophy, while overexpression promotes apoptosis." (PMID 37809621, 2023).
celiac disease (1 paper, 2015). An autoimmune genetic disorder with an unknown pattern of inheritance that primarily affects the digestive tract. "The NCALD gene expression in biopsies was decreased in celiac disease patients carrying the minor allele of SNP rs652008 (p = 0.005)." (PMID 26123480, 2015). "The gene APPL2 was down-regulated and NCALD up-regulated in both peripheral blood and the small intestine of celiac disease patients." (PMID 26123480, 2015). "The differential expression of NTS and PPP1R12B indicate a potential role for smooth muscle contractility and cell proliferation, whereas other genes like GLS, NCALD and INSR suggests involvement of nutrient signaling and energy homeostasis in celiac disease pathogenesis." (PMID 26123480, 2015). "The differential expression of NTS and PPP1R12B indicate a potential role for smooth muscle contractility and cell proliferation in celiac disease, whereas other genes like GLS, NCALD and INSR suggests involvement of nutrient signaling and energy homeostasis in celiac disease pathogenesis." (PMID 26123480, 2015).
diabetic nephropathy (1 paper, 2017). "NCALD, a calcium-binding protein, has been associated with diabetic nephropathy." (PMID 28077804, 2017).
epilepsy (1 paper, 2021). A brain disorder characterized by episodes of abnormally increased neuronal discharge resulting in transient episodes of sensory or motor neurological dysfunction, or psychic dysfunction. "Recent studies have reported that intellectual disability and epilepsy were detected in patients with NCALD deletion, indicating that NCALD could be a crucial gene in epilepsy." (PMID 34805265, 2021). "Among the 17 hub resistance genes, we found that NCALD and GPR56 were verified to be directly relevant to epilepsy in previous studies." (PMID 34805265, 2021).
lung adenocarcinoma (1 paper, 2023). A carcinoma that arises from the lung and is characterized by the presence of malignant glandular epithelial cells. "Interestingly, NCALD (neurocalcin delta) expression was lower in lung adenocarcinoma tissues, and patients with higher NCALD levels exhibited a higher survival rate." (PMID 37770991, 2023).
serous ovarian cancer (1 paper, 2021). "In advanced high-grade serous ovarian cancer, NCALD and LAMA3 have hypermethylation and low expression in chemoresistant patients." (PMID 34289901, 2021). "As a new biomarker of chemotherapy sensitivity, hypermethylation of NCALD and LAMA3 is associated with poor PFS in advanced high-grade serous ovarian cancer." (PMID 34289901, 2021). "In the tissue array composed of 132 advanced high-grade serous ovarian cancer patient samples, immunohistochemistry also showed that the expression of NCALD and LAMA3 in chemoresistant patients was lower than that of chemosensitive patients (57.89% VS 39.58%, P = 0.048; 54.67% VS 42.55%, P = 0.041)." (PMID 34289901, 2021). "In advanced high-grade serous ovarian cancer, ITGB6, NCALD and LAMA3 hypermethylation indicate chemotherapy resistance and poor prognosis." (PMID 34289901, 2021). "In advanced high-grade serous ovarian cancer, 8 CpGs (ITGB6:cg21105318, cg07896068, cg18437633; NCALD: cg27637873, cg26782361, cg16265707; LAMA3: cg20937934, cg13270625) remained hypermethylated in chemoresistant patients." (PMID 34289901, 2021). "We identified 3 new methylation genes (ITGB6, NCALD and LAMA3) with different chemotherapy outcomes in advanced high-grade serous ovarian cancer." (PMID 34289901, 2021). "In advanced high-grade serous ovarian cancer with complete debulking, PFS of 3 candidate CpGs (ITGB6:cg07896068; NCALD:cg27637873, cg16265707) hypermethylation patients was significantly shorter." (PMID 34289901, 2021). "For the first time, the role of DNA methylation in regulating the function of NCALD and LAMA3 genes in advanced high-grade serous ovarian cancer was pointed out." (PMID 34289901, 2021). "In advanced high-grade serous ovarian cancer with complete debulking (N = 37), PFS of 3 candidate CpGs (ITGB6:cg07896068; NCALD: cg27637873, cg16265707) hypermethylation patients was significantly shorter." (PMID 34289901, 2021).
cancer (7 papers, 2016 to 2025). A tumor composed of atypical neoplastic, often pleomorphic cells that invade other tissues. "Previous studies had found that NCALD was not only involved in cell apoptosis, cell cycle progression and other biological processes in several cancers, but also associated with the prognosis of cancers." (PMID 37770991, 2023). "Previous studies have reported that low expression of the NCALD gene is associated with the prognosis of some kinds of cancer." (PMID 31109331, 2019). "So far, little has been reported known about the relationship between NCALD and cancer, and the prognostic relationship between this gene and CN-AML has not been reported." (PMID 31109331, 2019). "Moreover, bioinformatic analysis of competing endogenous RNA (ceRNA) and mRNA interactions suggested that NCALD may regulate other genes: it can potentially behave like a ceRNA for 89 genes across over 20 different cancers." (PMID 37123549, 2023). "Subsequent studies show that NCALD might be involved in the pathogenesis of human cancer." (PMID 27027352, 2016). "For NCALD and OBSL1, only cancer cells expressed canonical protein-coding isoforms, while other cells expressed short noncoding isoforms." (PMID 38012143, 2023). "A review of the literature revealed that aberrant expression of CKMT1A, GCNT1, NCALD, NFKBIB, NOMO3/Nodal, SLC16A5, or TRPV2 was correlated with cancer." (PMID 31363162, 2019).
tumor (5 papers, 2016 to 2025). "This confirmed that lncRNA NCALD was significantly upregulated in patients with the luminal subtype, characterized by a tumor size greater than 2 cm and ER-positive status." (PMID 38291441, 2024). "qRT-PCR analysis revealed a significant increase in the expression of lncRNA NCALD in luminal BC tissues compared with that in adjacent non-tumor tissues." (PMID 38291441, 2024). "To further confirm whether MIDEAS-AS1 exerts tumor-suppressive functions via modulating NCALD, we co-transfected si-NCALD and MIDEAS-AS1-overexpressed plasmid in TNBC cell lines." (PMID 37770991, 2023). "Collectively, our results demonstrate that MIDEAS-AS1 serves as a tumor-suppressor in TNBC through modulating MATR3/NCALD axis, and MIDEAS-AS1 may function as a prognostic biomarker for TNBC." (PMID 37770991, 2023). "The expression levels of RAMP-AS1, miR-296-5p, CD44, CCND3, NCALD and MACF1 were detected in 40 tumor and adjacent tissue samples via RT-qPCR." (PMID 33281971, 2021). "Based on GEO data analysis, we detected upregulation of lncRNA NCALD in BC tissues compared to normal breast tissues, irrespective of tumor subtype (luminal or other types)." (PMID 38291441, 2024). "The expression levels of CD44, CCND3, NCALD, MACF1 and KCTD15 were downregulated in the vast majority of LUAD histological subtypes compared with in normal samples; additionally, they were differentially expressed according to tumor stage and nodal metastasis status." (PMID 33281971, 2021). "Furthermore, the expression levels of CD44, CCND3, NCALD, MACF1 and KCTD15 were downregulated in the vast majority of LUAD histological subtypes compared with in normal samples, and they were differentially expressed according to tumor stage and nodal metastasis status." (PMID 33281971, 2021). "Reverse transcription-quantitative PCR assays revealed that RAMP2-AS1, CD44, CCND3, NCALD and MACF1 expression was lower in tumor tissues than in normal tissues, while miR-296-5p expression was higher in tumor tissues compared with in normal tissues." (PMID 33281971, 2021).
neurological diseases (2 papers, 2019 to 2025). "While acting protective in SMA, NCALD reduction has also been associated with various neurological disorders." (PMID 30853885, 2019). "An example of an exon-level-specific eQTL is Neurocalcin Delta (NCALD), a brain-enriched protein associated with various neurological disorders." (PMID 40253403, 2025). "In conclusion, NCALD reduction acts protective in SMA and at the same time is associated with various neurological diseases." (PMID 30853885, 2019).
NCALD also shares sentences with these, for which no sentence is quoted: non-small cell lung carcinoma (3 papers); colorectal cancer (2); acute myeloid leukemia (1); Anxiety (1); autism (1); autosomal dominant deafness (1); cognitive decline (1); Cohen syndrome (1); depression (1); diabetes (1); gastric cancer (1); Intellectual disability (1); medulloblastoma (1); nasal obstruction (1); neuroblastoma (1); neurodevelopmental disorder (1); pancreatic endocrine tumor (1); primary ciliary dyskinesia (1); stress-related disorder (1); triple-negative breast carcinoma (1).